SMYD3 (SET and MYND domain containing 3)
Diseases named in the same sentence as SMYD3 in open-access papers (continued):
Sharing a sentence is not in itself a finding about the gene and the disease.
cancer (continued). "The pro-tumoral functions of SMYD3 have been well investigated in different cancer settings." (PMID 37386026, 2023). "In this scenario, the elucidation of the multifaceted role of SMYD3 in cancer may lead to new and more effective therapeutic approaches." (PMID 37954147, 2023). "SMYD3 may also contribute to Ras-driven cancers as seen in elevated lysine methyltransferase activity in pancreatic malignancies." (PMID 36838987, 2023). "As such, it can be hypothesized that SMYD3 oncogenic role is carried out at various timepoints throughout cancer progression in response to different stressor stimuli." (PMID 35495117, 2022). "Similarly, AKT1 and HSP90 (HS90A), which are also known SMYD3 targets and are included in Reactome pathways clustering in cancer hallmarks “tumor-promoting inflammation” and “resisting cell death”, respectively, also contain various P-tripeptides." (PMID 35495117, 2022). "The discovery of SMYD3 and recognition of its importance on the survival of liver and colon cancer cells have stimulated a number of studies to establish its solid connection with cancer progression." (PMID 36520265, 2022). "This approach is validated by the observation that known SMYD3 interactors, such as VGFR1, which is involved in cancer hallmark “inducing angiogenesis”, and ATM and BRCA2, which are involved in cancer hallmark “genome instability & mutation”, show a significant enrichment in P-tripeptides." (PMID 35495117, 2022). "Notably, based on different studies carried out by pharmacological companies and academic groups on SMYD3 cancer-related activity, novel and more efficient SMYD3 inhibitors have been generated." (PMID 36496998, 2022). "SMYD3, though known in other cancers, is yet to be explored in MB, to our knowledge." (PMID 35406445, 2022). "Next, to gain insight into novel SMYD3 cancer-related activities, we focused on the whole-proteome distribution of the P1-P19 tripeptides and assessed the biological function of each putative SMYD3 interactor to identify the most important candidates associated with cancer hallmarks." (PMID 36496998, 2022). "SMYD3 overexpression in several human cancers highlights its crucial role in carcinogenesis." (PMID 35495117, 2022). "However, because SMYD3 is also overexpressed in various RAS-independent cancers, the lysine methyltransferase SMYD3 likely operates through other oncogenic mechanisms in different types of cancer." (PMID 35819319, 2022). "Notably, RPB1 is a known SMYD3 interactor involved in various cancer hallmarks, namely “enabling replicative immortality”, “genome instability & mutation”, and “sustaining proliferative signaling”." (PMID 35495117, 2022). "Our findings serve as a proof-of-concept that activation of histone methyltransferases, such as EZH2, EHMT2, and SMYD3 might promote hepatocarcinogenesis by inducing enhancer aberration of crucial cancer-related genes." (PMID 35300417, 2022). "Based on this approach, we identified in silico five novel SMYD3 interactors selected for their enrichment in P-tripeptides and their prominent role in five cancer hallmark-related clusters for which no SMYD3 interactor was known to date." (PMID 35495117, 2022). "In particular, SMYD3 methylates AKT1 at lysine 14 in cancer cells, promoting its phosphoactivation." (PMID 35495117, 2022). "The oncogenic properties of SMYD3 have been reported in numerous cancer types." (PMID 35406445, 2022). "BCI-121 directly targets SMYD3 to inhibit proliferation in cancer cells with high SMYD3 expression." (PMID 35406445, 2022). "In particular, we searched for novel SMYD3 interactors involved in cancer-related pathways." (PMID 36496998, 2022). "To gain insight into novel SMYD3 cancer-related roles, here we performed a comprehensive in silico analysis to cluster all potential SMYD3-interacting proteins identified by screening the human proteome for the previously tested tripeptides, based on their involvement in cancer hallmarks." (PMID 35495117, 2022).
cancer (continued). "Growing evidence supports a key role for SMYD3 in tumorigenesis in several cancer types." (PMID 34503239, 2021). "Intriguingly, several studies revealed that SMYD3 exerts its oncogenic role primarily by interacting with and methylating non-histone proteins, through which it transactivates specific pathways involved in the survival and expansion of cancer cells." (PMID 34503239, 2021). "This is ideal from a drug discovery standpoint, as it means that SMYD3 inhibition could be an effective anti-cancer target with few off-target effects." (PMID 33637115, 2021). "Further studies are needed not only to gain a full comprehension of SMYD3-mediated mechanisms promoting cancer progression but also to gather stronger evidence in support of the effectiveness of novel therapeutic strategies based on the use of SMYD3i in specific patient subsets." (PMID 34503239, 2021). "Previous studies have shown that SMYD3 expression is increased in KRAS-mutated cancer, which may be due to the regulative effect of KRAS on SMYD3 gene transcription or protein stability." (PMID 34335697, 2021). "Moreover, future studies will have to focus on the design of novel inhibitors suitable for cancer patients, with the aim of making SMYD3 a druggable target in clinical practice." (PMID 34503239, 2021). "In particular, SMYD3 is known to regulate cancer cell growth and proliferation." (PMID 34842655, 2021). "Thus, SMYD3 appears as a genetic guardian of DNA damage checkpoint dynamics, driving cell cycle phase transition and promoting genomic protection of cancer cells." (PMID 34503239, 2021). "We performed CCK8, colony formation, cell cycle, apoptosis, and transwell assays to explore whether SMYD3-mediated S1PR1 activity was involved in cancer cell development and progression." (PMID 34301921, 2021). "These events, which are involved in carcinogenesis, could be an effect of SMYD3-mediated transcriptional regulation of cancer-related genes, such as MYC and CTNNB1, and components of the IL6-JAK-STAT3 pathway." (PMID 34503239, 2021). "This promising approach could be taken advantage of for therapeutic applications of SMYD3 inhibitors in cancer treatment." (PMID 34503239, 2021). "In this review, we focus on a specific member of the SMYD family, SMYD3, and we discuss its structure, tissue distribution, reported substrates, cancer-specific functions, and ongoing drug discovery efforts, with the goal to highlight its clinical implications and therapeutic possibilities." (PMID 33637115, 2021). "SMYD3 and NKD2DSV genes were associated with cancer patients with FCH (p < 0.05)." (PMID 33431054, 2021). "Recent studies provided evidence that SMYD3 may be an important biomarker for the diagnosis of several types of cancers and a potential target for drug discovery." (PMID 34503239, 2021). "In a recent report, we evaluated SMYD3 somatic alterations and mRNA expression in CRCs and PCs by analyzing publicly available human cancer data from The Cancer Genome Atlas (TCGA) dataset, which contains records for many cancer types, including multi-omics and standardized clinical information." (PMID 34503239, 2021). "It has been reported that SMYD3 overexpression in normal cells is sufficient to accelerate cell growth and trigger the activation of genes involved in the transformation and migration of cancer cells." (PMID 34503239, 2021). "It has been reported that SMYD3 plays a role in cancer development." (PMID 34587977, 2021). "In this scenario, SMYD3 overexpression reinforces DNA damage response in cells with intrinsic/genotoxic stress and hence promotes cancer progression, suggesting that it may also alter cell sensitivity to genotoxic cancer therapy." (PMID 34503239, 2021). "The inhibition of SMYD3 is promising for the therapeutic treatment of these cancer types." (PMID 35076487, 2021). "In this section, we will review reported functions of SMYD3 in various cancer types." (PMID 33637115, 2021).
cancer (continued). "Several lines of evidence support the hypothesis that SMYD3 upregulation has a key role in tumorigenesis and cancer development in a number of human malignancies." (PMID 34503239, 2021). "However, since this discovery, other histone (H4K5 and H4K20, for example) and non-histone (VEGFR, HER2, MAP3K2, ER, and others) substrates of SMYD3 have been described, primarily in the context of cancer." (PMID 33637115, 2021). "Further insights into the oncogenic role of SMYD3 and its targeting of different synergistic oncogenic signals may be beneficial for effective cancer treatment." (PMID 31935919, 2020). "Furthermore, SMYD3 has been shown to interact with transcription factors involved in cancer, such as the estrogen receptor (ER)." (PMID 31935919, 2020). "Hence, SMYD3 orchestrates cancer cells proliferation and migration influencing oncogenes, tumor suppressors, cell cycle related-genes and EMT factors, thus promoting tumorigenesis in different interconnected ways." (PMID 31935919, 2020). "Furthermore, SMYD3 is a component of the SMYD3/H3K4Me3/RNA pol-II complex that enhances the transcription of genes that are involved in cancer-related pathways." (PMID 31952344, 2020). "Many studies have advocated a role for SMYD3 in the regulation of cancer cell proliferation." (PMID 31935919, 2020). "This hypothesis is supported by different studies where SMYD3 has been found to interact with factors belonging to complexes that influence proliferative pathways, in cancer cell extracts." (PMID 31935919, 2020). "Collectively, these studies indicate SMYD3 as a potential therapeutic target for cancer treatment." (PMID 33333978, 2020). "SMYD3, a histone H3-K4 specific methyltransferase, is an example of histone modification which is considered a crucial epigenetic factor contributing to the development of various human cancers, including liver cancer." (PMID 32071406, 2020). "SMYD3 expression is abnormally elevated in over 15 types of cancers." (PMID 31737645, 2019). "Furthermore, SMYD3 maintains the self-renewal capacity of a subset of cancer stem cells (CSCs) by regulating the expression of the master stem cell regulator ASCL254." (PMID 31754141, 2019). "SMYD3’s role in cancer involves regulating cell proliferation and cell cycle progression." (PMID 31754141, 2019). "SMYD3 is frequently overexpressed in cancer cells and enhances cell proliferation." (PMID 31754141, 2019). "The example of the Smyd3 locus demonstrates the potential for time course mutation analysis to not only identify cancer drivers, but also potential targets that while not mutated, are essential for tumor cell growth." (PMID 29985390, 2018). "SMYD3 is a methyltransferase highly expressed in many types of cancer." (PMID 28630472, 2017). "Interestingly, the functional enrichment annotation map contains several cell motility‐related GO terms, for example, ‘cell–substrate adhesion’ and ‘cell–matrix adhesion’, indicating a function for SMYD3 in cancer cell metastasis." (PMID 28781952, 2017). "SMYD3 was a well-known oncogene involved in human malignant tumors." (PMID 29029425, 2017). "SMYD3 plays a key role in cancer cell viability, adhesion, migration and invasion." (PMID 28050603, 2017). "Based on this preclinical evidence, SMYD3 has been under investigation as an anticancer target for the identification of specific drug compounds, and SMYD3 inhibitors that suppress the growth of SMYD3-overexpressing cancer cells were recently reported in the literature." (PMID 29348866, 2017). "SMYD3 upregulates multiple cancer genes through H3K4 trimethylation." (PMID 28050603, 2017). "Methylated MAP3K2 links SMYD3 to Ras-driven cancer promoting cell proliferation and tumorigenesis." (PMID 28050603, 2017). "Our results explored a novel mechanism relevant to activation of the AKT1 signaling pathway, and it may be an appropriate strategy to target SMYD3-mediated AKT1 methylation for the development of anti-cancer treatment." (PMID 27626683, 2016).
cancer (continued). "In addition, the Cancer Genome Atlas (TCGA) database indicates frequent amplification of SMYD3 in various types of cancer." (PMID 27626683, 2016). "Knockdown of SMYD3 resulted in a significant reduction in cancer cell growth." (PMID 27790639, 2016). "To date, SMYD3 has been found to be overexpressed in over 15 types of cancers." (PMID 27790639, 2016). "Overexpression of SMYD3 has been repeatedly shown to promote cancer cell growth." (PMID 27790639, 2016). "This indicates that SMYD3 might be involved in cancer through suppression of cancer immunity and dampen anti-tumor immune response via promoting Foxp3-dependent immune suppressive pathways." (PMID 27790639, 2016). "However, growth-stimulatory and proliferative genes appeared preferentially down-regulated under SMYD3 knockdown conditions, suggesting that SMYD3-mediated activation of target genes is more functional in cancer cells." (PMID 26350217, 2015). "Thus the fact that PC4 stably associates with SMYD3 in our purification prompted us to study the possible influences of PC4 on SMYD3-mediated transactivation and cancer cell proliferation/invasion." (PMID 26350217, 2015). "Although these effects could be indirect, the striking correlation between the levels of SMYD3 and H3K4me3 at target genes suggests that SMYD3 is a prominent regulator of H3K4me3 in the cancer cell lines." (PMID 26350217, 2015). "However, our examination of H3K4me3 at SMYD3 target genes revealed that SMYD3 knockdown has a major impact on H3K4me3 levels in the cancer cell lines employed in this study." (PMID 26350217, 2015). "As expected, ChIP and quantitative PCR (ChIP-qPCR) assays showed high levels of SMYD3 occupancy at the SMYD3 binding elements in mock-depleted bladder (J82 and T24)/colon (HCT116 and CaCO2) cancer cells, but SMYD3 levels were markedly decreased after SMYD3 knockdown." (PMID 26350217, 2015). "Among the down-regulated genes with LTR-001 stands SMYD3, which encodes a lysine methyltransferase involved in the methylation of MAP3K2, increasing MAP kinase signaling and promoting the formation of Ras-driven carcinomas." (PMID 26510915, 2015). "Hence, we selected the SMYD3 candidate gene based on expression and possible biological relevance to cancer." (PMID 20525348, 2010). "Smyd3 has been noted for its involvement in cancer cell proliferation." (PMID 16805913, 2006). "Indeed, understanding the molecular basis of SMYD3 function in cancer settings may help develop effective therapeutic strategies." (PMID 40588481, 2025). "Our data revealed an enrichment of SMYD3 in residual tumors that had not undergone complete regression after irinotecan exposure, further suggesting that increased expression of SMYD3 may contribute to the cellular mechanisms that mediate cancer chemoresistance." (PMID 38812026, 2024). "Moreover, we recently showed that SMYD3 has a protective role during cell response to genotoxic stress by promoting the restoration of damaged DNA via the HR repair pathway, thereby sustaining cancer cell genomic stability and tumor progression." (PMID 38812026, 2024). "The inhibition of SMYD3 may prove to be desirable for the clinical management of various cancers." (PMID 36838987, 2023). "Overall, a growing body of evidence indicates that SMYD3 is an essential epigenetic regulator that methylates histone and non-histone substrates, orchestrating protein-protein and protein-DNA interactions; however, its epigenetic role in cancer is not fully understood yet." (PMID 37954147, 2023). "The general plus of our P-tripeptides is that they probe different segments of the human proteome and might be taken advantage of to design pharmacological inhibitors of SMYD3 oncogenic PPIs as a means to alter the composition of multiprotein complexes involved in cancer hallmarks." (PMID 35495117, 2022).
cancer (continued). "Because RNF113A acts upstream of the alkylation damage repair pathway by recruiting the ASCC complex, we reasoned that an upregulated response to alkylation damage may promote cancer cell tolerance to alkylating agents and explained the impact of SMYD3 in our SCLC and xenograft models." (PMID 35819319, 2022). "EZH2, EHMT2, and SMYD3 are vital epigenetic regulators that could be targeted for cancer therapy." (PMID 35300417, 2022). "Consequently, we inferred that subjects with FCH carrying SMYD3 or NKD2 gene deletions may have a higher cancer incidence." (PMID 33431054, 2021). "In this study, we present and compare the tertiary structures of the subdomains in SMYD3 to the SET domains in other proteins to inform the development of specific small molecule inhibitors that could be useful in the understanding and treatment of SMYD3-positive cancers." (PMID 35076487, 2021). "In addition, SMYD3 overexpression was associated with advanced T stage and lower survival rates in patients with CRC, thereby identifying it as an independent prognostic factor for this type of cancer." (PMID 34503239, 2021). "Indeed, cancer cells treated with the SMYD3 inhibitor BCI-121 accumulated in the S phase of the cell cycle, suggesting that SMYD3 might be required for proper cell cycle progression through the S/G2 boundary." (PMID 31935919, 2020). "Taken together, these opposing data about the effect of SMYD3 on different stages of the cell cycle suggest that SMYD3 might play different roles at different stages of the cell-cycle and impact different types of carcinomas in distinct ways." (PMID 31935919, 2020). "Recent reports may also indicate a role for SMYD2 and SMYD3 in the systemic response to cancer." (PMID 29856759, 2018). "Additionally, SMYD3 has been described as an oncogenic methyltransferase since 2004, and many studies have further supported its significance in human tumorigenesis in multiple cancer types." (PMID 29348866, 2017). "Smyd3 is over-expressed in hepatocellular and colorectal carcinomas; recent work showed that it is required for the development of those tumors through the up-regulation of a set of cancer promoting genes, and also enhances the tumorigenic capacity of esophageal squamous cell carcinoma." (PMID 27655694, 2016). "On the basis of these results, Lys 14 of AKT1 is likely to be a key amino acid to determine AKT1 activity through the electrostatic attraction with Glu 17 and the interaction with phosphoinositides; SMYD3-mediated methylation of Lys 14 may trigger the constitutive activation of AKT1 in cancer cells." (PMID 27626683, 2016). "Therefore, we examined the biological significance of SMYD3 on the AKT pathway in cancer cells." (PMID 27626683, 2016). "Thus, SMYD3 has emerged as yet another promising target for therapeutic intervention in cancer." (PMID 24710145, 2011). "We performed a head-to-head comparison of N-acetylgalactosamine (GalNAc)-conjugated small interfering RNA (siRNA)-mediated inhibition of five genes (CDK1, PD-L1, CTNNB1, SMYD3, ANLN) to prevent cancer in four distinct autochthonous HCC mouse models." (PMID 40704506, 2025). "SREBP1 is the downstream transcription factor of SMYD3 that regulates CD47 expression in ccRCC, and CD47 is well characterized as an inhibitory checkpoint target expressed on the surface of cancer cells." (PMID 40548645, 2025). "Our results show that SMYD3 activity mediates DDR in response to chemotherapeutics (CHTs) and that its inhibition with the covalent inhibitor EM127 sensitizes cancer cells to chemotherapy." (PMID 38812026, 2024). "The research presented in this review indicates that SMYD family members are important targets for cancer therapy, with SMYD2 and SMYD3 proposed as more effective targets for cancer treatment." (PMID 39482529, 2024). "The number of studies on SMYD4 and SMYD5 in the field of cancer has increased, although relatively few reports have compared SMYD4 and SMYD5 to SMYD2 and SMYD3." (PMID 39482529, 2024).